PDIA4 (protein disulfide isomerase family A member 4)
Diseases named in the same sentence as PDIA4 in open-access papers (continued):
Sharing a sentence is not in itself a finding about the gene and the disease.
colorectal cancer (2 papers, 2022 to 2025). A primary or metastatic malignant neoplasm that affects the colon or rectum. "Finally, we found that in tumors isolated from colorectal cancer patients, PDIA4 and DNAJB12 are highly expressed compared to their healthy tissues; this expression is associated with the induction of the UPR." (PMID 41120732, 2025).
endothelial dysfunction (2 papers, 2023 to 2024). In vascular diseases, endothelial dysfunction is a systemic pathological state of the endothelium (the inner lining of blood vessels) and can be broadly defined as an imbalance between vasodilating and vasoconstricting substances produced by (or acting on) the endothelium. "The results from this study warrant further investigation into the therapeutic potential of PDIA-4 for treating impaired autophagy-, impaired endothelial dysfunction-, and/or EndMT-associated diseases, such as atherosclerosis and organ fibrosis." (PMID 38612722, 2024).
gastric cancer (2 papers, 2021 to 2025). A primary or metastatic malignant neoplasm involving the stomach. "More interestingly, QKI has been found to bind to the introns 2 and 4 of PDIA4 mRNA resulting in a novel circRNA generation in gastric cancer." (PMID 40263288, 2025). "Among these RBPs, QKI was identified as the only protein reported to generate another circRNA by binding to PDIA4 introns 2 and 4 in gastric cancer cells." (PMID 40263288, 2025). "Clinical studies have shown that the level of ApoB/ApoA1 in gastric cancer patients is negatively correlated with the survival rate, while PDIA4 is positively correlated with the survival rate of gastric cancer patients." (PMID 34476221, 2021).
renal carcinoma (2 papers, 2022 to 2024). A carcinoma arising from the epithelium of the renal parenchyma or the renal pelvis. "The distinct metabolic profile of renal cancer is intimately associated with its sensitivity to ferroptosis, with multiple molecular mechanisms implicated in the regulation of ferroptosis in renal cancer, including PDIA4, GPX4, KLF2, ACSL3, and AIM2." (PMID 39092291, 2024).
thyroid cancer (2 papers, 2023 to 2025). "Clinically, an abnormal level of PDIA-4 expression has been observed in breast, liver and thyroid cancers." (PMID 39803361, 2023).
xerostomia (2 papers, 2020 to 2023). Dryness of the mouth resulting from reduced salivary secretion. "In our opinion, decreased expression of genes encoding CANX and PDIA4, in SS sufferers with and without xerostomia compared to HS can lead to accumulation of misfolded proteins in the ER and changes in the quantity and quality of salivary proteins." (PMID 33066537, 2020). "In SS patients both with xerostomia (sicca) and without xerostomia (non-sicca), TMED10, PDIA4, CANX, APP, and TMBIM6 expression was lower than in HS." (PMID 33066537, 2020).
amyloid disease (1 paper, 2022). "This further highlights the potential for enhancing the activity of key ER quality control factors including BiP or PDIA4 through mechanisms such as ATF6 activation to ameliorate pathologic extracellular aggregation of TTR implicated in amyloid disease pathogenesis." (PMID 35626697, 2022). "To evaluate whether PDIA4 or BiP overexpression similarly reduced amyloidogenic TTR secretion in an amyloid disease relevant cell line, we monitored total and aggregate FTTTRA25T in conditioned media prepared on liver-derived HepG2 cells." (PMID 35626697, 2022). "For example, strategies that enhance PDIA4 chaperoning activity could offer new opportunities to preferentially reduce the secretion and toxic aggregation of TTR in the context of TTR amyloid diseases." (PMID 35626697, 2022).
autoimmune disease (1 paper, 2020). A disorder resulting from loss of function or tissue destruction of an organ or multiple organs, arising from humoral or cellular immune responses of the individual to their own tissue constituents. "Another mutual pathway comprising PDIA4, APP and CANX genes is an ER dependent mechanism observed in both neurodegenerative and autoimmune diseases." (PMID 33066537, 2020).
epilepsy (1 paper, 2024). A brain disorder characterized by episodes of abnormally increased neuronal discharge resulting in transient episodes of sensory or motor neurological dysfunction, or psychic dysfunction. "Surprisingly, we also identified many differential proteins such as UGGT2, SEMG1, PDIA4, ROR1, NIF3L1, and ITIH4, that have not previously been directly reported with epilepsy." (PMID 38585359, 2024).
Impaired glucose tolerance (1 paper, 2022). An abnormal resistance to glucose, i.e., a reduction in the ability to maintain glucose levels in the blood stream within normal limits following oral or intravenous administration of glucose. "We found that serum PDIA4 levels were associated with IR and inflammatory cytokines levels in subjects with normal or impaired glucose tolerance." (PMID 36619574, 2022).
lung squamous cell cancer (1 paper, 2023). "CAT, ENO1, NQO1, P4HB, and PDIA6 were unique to LUAD, while CAV1, GAPDH, GPX2, GPX3, and PDIA4 exhibited consistent trends in differential expression in both LUAD and lung squamous cell cancer, significant prognostic survival prediction (p<0.05), and excellent classification effectiveness." (PMID 37955007, 2023).
neuroblastoma (1 paper, 2018). Neuroblastoma (NB) is the most common solid, extracranial childhood tumor. "The small molecule BIX induces BiP expression through an ATF6-dependent mechanism, but does not substantially induce expression of other ATF6 target genes, such as Grp94 and PDIA4 in SK-N-SH neuroblastoma cells." (PMID 30481215, 2018).
non-small cell lung carcinoma (1 paper, 2022). A group of at least three distinct histological types of lung cancer, including non-small cell squamous cell carcinoma, adenocarcinoma, and large cell carcinoma. "Interestingly, the combination of CALR and disulfide isomerase (PDIA3) was found to be a potential prognostic biomarker for non-small-cell lung cancer, which coincides with our finding of the upregulation of PDIA4 in ADC and PDIA3 and PDIA4 in SCC tissues." (PMID 35512017, 2022).
ovarian tumors (1 paper, 2023). "Similarly, low expression of PDIA4 has been reported to be associated with shorter survival in ovarian tumors, especially in drug-resistant tissues." (PMID 37240946, 2023).
prion disease (1 paper, 2025). A transmissible disease that is caused by a protein that is able to induce abnormal folding of normal cellular proteins, leading to characteristic spongiform brain changes, which are associated with neuronal loss without an inflammatory response. "Therefore, the identification of PDIA4 in this study and its strong links to the UPR are in keeping with the emerging theme in the prion disease field that a dysregulated UPR is a driver of neurotoxicity." (PMID 39865733, 2025).
prostate carcinoma (1 paper, 2024). A carcinoma that arises from epithelial cells of the prostate gland. "It was revealed that modulating PDIA4 expression in cancer cells allowed the cells to grow by regulating caspase 3 and 7, docetaxel resistance was induced by PDIA4 activation and inhibited prostate cancer cell apoptosis, while PDIA4 inactivation restored classical mitochondrial apoptosis." (PMID 38167446, 2024).
synovitis (1 paper, 2020). Inflammation of a synovial membrane. "Although ERp29, PDIA4, Protein ERGIC-53 and GANAB proteins were highly positively correlated in our work with the histological inflammatory score, their presence and their role in the pathophysiology of synovitis have not yet been described." (PMID 32887899, 2020).
tumor (29 papers, 2013 to 2025). "Next, Rag1–/‐ and Rag1–/‐ Pdia4–/‐ mice bearing GK1 tumours were used to investigate the function of Pdia4 in T cell‐ and B cell‐implicated tumour development because T and B cells are deficient due to Rag1 ablation." (PMID 35170261, 2022). "Moreover, P4HB, PDIA3, and PDIA4 were found to be up-regulated in ovarian cancer and associated with the tumor grade and poor prognosis." (PMID 32023222, 2020). "Evidence has shown that PDIA4 has dual functions in tumors; it can exert anti-tumor effects while also potentially promoting tumor development." (PMID 41185082, 2025). "In vitro experiments involving PDIA4 downregulation resulted in a significant reduction of proliferation and increased the apoptosis of tumor cells after RT as well as increasing its sensitivity of RT and vice versa." (PMID 38167446, 2024). "For this purpose, the stable MDA-MB-231 cell line with PDIA4 expression knockdown was subcutaneously injected into nude mice to construct a xenograft tumor mouse model." (PMID 38167446, 2024). "Here, PDIA4 expression is significantly higher in TNBC tumor tissues than in normal tissues adjacent to the tumor." (PMID 38167446, 2024). "Based on paired clinical specimens of TNBC patients, we found that PDIA4 expression was significantly higher in tumor tissues compared to adjacent normal tissues." (PMID 38167446, 2024). "By interacting with a variety of immunological components, PDIA4 cold promote an immunosuppressive microenvironment in tumor." (PMID 38159261, 2023). "On the basis of the levels of lncRNAs FAM225B and PDIA4 in tumor cell lines, we chose the SKOV3 and OVCAR-3 cell lines for further research." (PMID 37720188, 2023). "Periodical flux monitoring demonstrated that xenograft tumors with LV-PDIA4 exhibited higher total flux compared to the LV-Ctrl, indicating that PDIA4 drives greater progressive tumor growth in vivo." (PMID 36997943, 2023). "Bioinformatical analyses based on clinical tumor samples and database indicated a positive correlation exists between PDIA4 and PERK/ATF4/SLC7A11 signaling pathway, as well as the malignant prognosis of RCCs." (PMID 36906674, 2023). "The body weights of all mice were recorded every three days after tumor implants, and the line graphs indicated that PDIA4 overexpression tumors conferred mice a more rapid reduction in body weight starting from approximately 15 days to the endpoint." (PMID 36997943, 2023). "PDIA4 is a novel ER stress chaperone that regulates adiponectin expression and inflammation in adipose tissue, and it is also involved in tumour progression by affecting apoptosis." (PMID 36291587, 2022). "CD31 in WT and Pdia4–/‐ mice bearing GK1 tumours was low (5%–10%) in the IHC and flow cytometry data." (PMID 35170261, 2022). "Immunoblotting data showed that subcutaneous stromal cells, isolated from non‐tumour bearing WT mice, had a lower level of Pdia4 than GK1 cancer cells grown in culture (SC versus GK1)." (PMID 35170261, 2022). "Median survival days in GK1 tumour‐bearing WT and Pdia4–/– mice were 45 days and 68 days, respectively." (PMID 35170261, 2022). "The connection of PDIA4 and OGN with tumor progression is relatively recent, PDIA4 has been found overexpressed in a cohort of EOC patients, and associated with poor prognosis, cell gowth and resistance." (PMID 35197484, 2022). "Since Pdia4 and Stat3 were present in stromal cells and tumour cells, CyTOF data showed that WT stroma had a higher level of phospho‐Stat3, Vegfa, Vegfb and Vegfc than Pdia4–/– stroma." (PMID 35170261, 2022). "A closer analysis of stromal cells showed that GK1 tumour‐bearing WT mice had a slightly higher proportion of MDSC in tumour sites than GK1 tumour‐bearing Pdia4–/– mice (left)." (PMID 35170261, 2022). "Consistently, WT mice bearing GK1 tumours had more lung metastasis than Pdia4–/– mice bearing GK1 tumours." (PMID 35170261, 2022).
tumor (continued). "Next, we studied the in vivo function of Pdia4 in tumour development using GK1 tumour‐bearing WT and Pdia4–/– mice." (PMID 35170261, 2022). "Accordingly, GK1 tumour‐bearing Rag1–/‐ mice that received Pdia4–/– T and B cells had smaller tumour volume and tumour weight than those that received WT T and B cells." (PMID 35170261, 2022). "To date, the contribution of tumour Pdia4 versus host Pdia4 in tumour development has been poorly studied." (PMID 35170261, 2022). "Consistently, GK1 tumours in Pdia4–/– mice had a smaller tumour volume and tumour weight than those in WT mice." (PMID 35170261, 2022). "A closer analysis of stromal cells showed that GK1 tumour‐bearing WT mice had more MDSC, B cells, T cells and other types of leukocytes at tumour sites than GK1 tumour‐bearing Pdia4–/– mice (middle)." (PMID 35170261, 2022). "Differential expression analysis of the hyperexpanded clones compared to all other clones revealed an elevated expression of tumor promoting factors/oncogenes (HSPA5, PDIA4, MANF, PPIB) and a gene associated with malignant B cell clones (CD63)." (PMID 36153593, 2022). "As a result, GK1 tumour‐bearing Rag1–/‐ mice that received Pdia4–/– T and B cells had better survival than those that received WT T and B cells." (PMID 35170261, 2022). "A previous study found that PDIA4 participates in tumor progression by influencing cell apoptosis and DNA repair mechanisms." (PMID 35678681, 2022). "To explore the type and function of stromal cells that host Pdia4 affects, we compared the cell composition and function of tumour stromal cells in WT and Pdia4–/‐ mice bearing GK1 tumours." (PMID 35170261, 2022). "We found that Pdia4–/– mice bearing GK1 tumours had better survival than WT mice bearing GK1 tumours." (PMID 35170261, 2022). "PDIA4 facilitates tumor cell growth via inhibiting the degradation and activation of procaspases 3 and 7 via their mutual interaction in a CGHC-dependent manner." (PMID 34476221, 2021). "Only Pdia4 mRNA was downregulated in the tumours of PlGFKO mice compared to their wild type littermates (p < 0.05)." (PMID 26753564, 2016). "In the tumor tissues, the protein levels of PDIA4 and DNAJB12 were also higher than normal tissues." (PMID 41120732, 2025). "Results showed that tumor tissues expressed significantly more PDIA4 mRNA than adjacent tissues." (PMID 38167446, 2024). "Moreover, PDIA4 knockdown suppressed tumor growth xenograft model in vivo, which was accompanied by an increase in apoptosis and promoted tumor growth inhibition after radiotherapy." (PMID 38167446, 2024). "IHC analysis of xenograft tumors indicated stronger staining of VEGFA and CD31 in LV-PDIA4 xenograft tumors, which indicated tumor-derived PDIA4 could promote VEGFA secretion and angiogenesis in vivo, as we had speculated." (PMID 36997943, 2023). "The XBP1/PDIA4/VEGFA regulatory axis may be responsible for how GBM cells obtain nutrients within the poor tumor microenvironment by accelerating angiogenesis." (PMID 36997943, 2023). "Together, these data demonstrated that Pdia4 positively controlled tumour development in mice." (PMID 35170261, 2022). "Consistently, Pdia4–/– mice had a smaller tumour volume and a lower tumour weight than WT mice." (PMID 35170261, 2022). "In addition, GK1 tumour‐bearing WT mice had more Treg cells than GK1 tumour‐bearing Pdia4–/– mice (right)." (PMID 35170261, 2022). "Furthermore, IHC staining data showed that GK1 tumours in Pdia4–/– mice had a lower protein level of Vegfa, Vegfb, Vegfc and phosphao‐Stat3 than those in WT mice." (PMID 35170261, 2022). "This evidence highlights that the role of PDIA4 in tumor might depend on the specific tumor type." (PMID 41185082, 2025). "However, the partners and/or substrates of Pdia4 are largely unknown, and even less is known about its tumour promotion mechanism." (PMID 35170261, 2022).
tumor (continued). "Previous studies have shown that the expression of PDIA4 is a self-protective response induced by ERS, which can mediate oxidative protein folding, inhibit apoptosis, and promote tumor progression by combining and degrading misfolded proteins." (PMID 38140584, 2023). "Data showed that expression of PDIA4 was increased in RCCs compared with the control, both in the RCC cell lines and human tumor tissues." (PMID 36906674, 2023). "We first compared the expression of PDIA4 in different RCC cell lines and control HK-2 cells, as well as in the RCC tumor and adjacent normal tissues." (PMID 36906674, 2023). "The result of the analysis revealed the expressional level of PDIA4, ATF4, and SLC7A11 in the RCC tumor is higher than the one in the adjacent normal tissue, respectively." (PMID 36906674, 2023). "This is coherent with the results of our dataset analysis, in which we found they showed a strong correlation with the tumor phenotype, with TOP1 and PDIA4 positively correlating and OGN being negatively correlated." (PMID 35197484, 2022). "The data were consistent with the discovery showing that WT T and B cells were more immunologically suppressive than Pdia4–/– T and B cells in GK1 tumour‐bearing mice." (PMID 35170261, 2022). "The corresponding heat map further proved that HSP90B1 was positively correlated with the six genes (HSPA5, PDIA3, MANF, PDIA4, CALR, and PDIA6) in various tumours." (PMID 36291587, 2022). "Next, mass flow cytometry (CyTOF) was used to confirm the protein level of Pdia4, Vegfa, Vegfb, Vegfc and phospho‐Stat3 in stromal subsets of GK1 tumour‐bearing WT and Pdia4–/– mice." (PMID 35170261, 2022). "Thus, PDIA4 might be connection between activated platelets and tumor progression." (PMID 34635181, 2021). "Conversely, a significant positive correlation was observed between PDIA4 expression and the IC50 values of 53 anti-tumor drugs, such as Dactinomycin, Epirubicin, Irinotecan, Mitoxantrone, Topotecan, Olaparib, Sabutoclax, Oxaliplatin, Camptothecin and Teniposide (P < 0.05)." (PMID 41185082, 2025). "In vitro, PDIA4 knockdown not only increased apoptosis of tumor cells with/without radiotherapy, but also decreased the ability of proliferation." (PMID 38167446, 2024). "The results of this study indicate that PDIA4 is an oncoprotein that promotes TNBC progression, and targeted therapy may represent a new and effective anti-tumor strategy, especially for patients with radiotherapy resistance." (PMID 38167446, 2024). "Based on these findings, investigating the role of these interactions among P4HB, PDIA4 and PDIA6 in driving aggressive tumor phenotypes, such as proliferation, invasion and metastasis, could uncover potential targets for anti-metastatic therapies." (PMID 38029391, 2023). "Western blot analysis of the tumor samples showed that ipomoeassin F significantly decreased the levels of PDAI6 and PDIA4 proteins, demonstrating the blocking effect of ipomoeassin F on PDIA6 and PDIA4 in vivo." (PMID 37705743, 2023). "However, GK1 tumour‐bearing WT mice had more GK1 cells and leukocytes in tumour sites than GK1 tumour‐bearing Pdia4–/– mice (right)." (PMID 35170261, 2022). "As expected, CyTOF data showed that Pdia4 was only expressed in the stromal cells of GK1 tumour‐bearing WT but not Pdia4–/– mice (1st row)." (PMID 35170261, 2022). "Similarly, Pdia4–/– mice bearing B16F10 and CT26 tumours had better survival than WT mice bearing B16F10 and CT26 tumours." (PMID 35170261, 2022). "Accordingly, the activation of Stat3 and expression of Vegfa, Vegfb, and Vegfc in GK1 tumours between Rag1–/‐ and Rag1–/‐ Pdia4–/– mice were not altered." (PMID 35170261, 2022). "These genes likely function as downstream effectors of STAT3 in GBM to regulate not only cell proliferation (e.g., GAS7, IGFBP2, MEOX2 and MXI1), and but also tumor-stroma interactions by modulating protein secretion (e.g., ANXA1, ARL4C, EMILIN1, EMP2, EXTL3 and PDIA4)." (PMID 29774125, 2018).
tumor (continued). "Based on the TCGA database, we compared the mRNA expression of PDIA4, ATF4, SLC7A11, and PERK between RCC tumor and adjacent normal tissue." (PMID 36906674, 2023).